FAP (fibroblast activation protein alpha)
Diseases named in the same sentence as FAP in open-access papers (continued):
Sharing a sentence is not in itself a finding about the gene and the disease.
tumor (continued). "A case example with an available biopsy performed shortly after the performed PET/CT scans provides a potential explanation for tumour heterogeneity: Tumour dedifferentiation was associated with loss of PSMA and PSMA-/FDG + /FAP + mismatch on PET scans." (PMID 39207485, 2024). "It has a high radiolabeling rate and good in-vitro stability with specific uptake ability for tumor cells overexpressing FAP." (PMID 39281380, 2024). "On the other hand, we did not observe significant correlations of other stromal markers, CD31 and FAP, with tumour stage." (PMID 39022761, 2024). "The in vivo profile of the anti-FAP-α sdAb, [18F]FB-4AH29, was investigated in TC-1-hFAP-α tumour bearing mice by a similar protocol, including micro-PET/CT imaging at 1 h p.i. and dissection analysis at 1.5 h p.i., and compared to [18F]FB-R3B23." (PMID 39048805, 2024). "The serine protease FAP detected on the surface of CAFs is tumor-specific in their expression pattern and has low overall survival across various tumors." (PMID 39579201, 2024). "A recent study developed a radio-labelled FAP inhibitor probe, which was able to track FAP expression on tumor cells and stromal cells in the TIME with a high target-to-background ratio." (PMID 38167055, 2024). "The results revealed significant differences between the tumor and paratumor tissues regarding the expression of FAP, secreted protein acidic and cysteine rich (SPARC), and tenascin C (TNC), which are closely related to HSCs’ function." (PMID 38740736, 2024). "In addition, due to the association of FAP with worse prognosis, invasion, metastasis, and treatment resistance in several cancers, the expression level of the FAP marker can be used as a biomarker in determining prognosis, recurrence, and diagnosis of tumor status." (PMID 39030445, 2024). "In this study, we determined that FAP correlates with tumor metastasis and shortened survival of NSCLC patients." (PMID 38459511, 2024). "In our prior work, we examined FAP expression across various tumor types and its link with clinical outcomes." (PMID 39035007, 2024). "Moderate-strong FAP expression in the tumor stroma was present in 93.1% (54/58) of CCA, 60.7% (17/28) of metastatic HCC, 29.6% (42/142) of primary HCC, 21.1% (4/19) of FNH and 11.6% (3/26) of HCA." (PMID 39664608, 2024). "Currently, an improved in vivo tumor retention up to three days has been shown with the cyclic peptide FAP-2286, resulting in improved FAP-TRT efficacy." (PMID 39073475, 2024). "Under pathological conditions, FAP expression is significantly elevated in the tumor stroma of breast, lung, colorectal, prostate, gastric, pancreatic, thyroid, cervical, and urothelial cancers." (PMID 39765634, 2024). "In 138 pairs of matched cancer and adjacent tissues, the proportion of CALB2+, CK19+CALB2+, and FAP+CALB2+ cells significantly increased in tumor tissues." (PMID 39358777, 2024). "This is supported by a separate study in NSCLC where CAFs expressing FAP and αSMA were also shown to be located closer to tumour nests than those only FAP+." (PMID 38582812, 2024). "The tumor-specific expression and its critical overall survival suggest the inhibitors of FAP for potential cancer therapeutic intervention and hindering tumor microenvironment-driven cancer progression." (PMID 39579201, 2024). "Both the alpha isoforms of the Folate Receptor (FR) and Fibroblast Activation Protein (FAP) are established tumour markers." (PMID 39048805, 2024). "Next, by evaluating the distribution of fibroblasts in tumor border samples, we found that FAP+ CAFs were more likely to be enriched at the tumor border in HCC samples while diffusely scattered in ICC." (PMID 39239526, 2024). "Remarkably, FAP expression emerges as a significant prognostic marker in numerous tumor types, often portending unfavorable outcomes, as exemplified by pancreatic ductal cancer and colorectal cancer (CRC)." (PMID 39035007, 2024).
tumor (continued). "These ECTs, which include immunosuppressive and immuno-permissive variants, encompass specific FAP+ CAF clusters and immune cell populations that are situated at discrete distances from tumor conglomerates and vascular structures." (PMID 39439806, 2024). "Its 177Lu-radiolabeled counterpart FAPI-02 was rapidly internalized into FAP-expressing cells and exhibited high tumor uptake in mice bearing HT-1080-FAP (epithelial) or SK-LMS-1 (vulvar) cell xenografts." (PMID 39765634, 2024). "For example, at a high (5:1) E:T ratio, NT‐T cells supplemented with IL‐2 induced as much tumor cell killing as FAP‐CAR‐T cells." (PMID 38975278, 2024). "In the xenografts, FAP expression was observed in the tumor cells as well as in what appeared to be the stroma." (PMID 39519118, 2024). "These tumor cell lines were co‐cultured with FAP‐CAR‐T cells or CAR‐T cells targeting an irrelevant antigen (EphA3) for 48 h, and the level of IL‐2 in the culture supernatant was measured by ELISA." (PMID 38975278, 2024). "Radiopharmaceutical therapies targeting fibroblast activation protein (FAP) have shown promising efficacy against many tumor types." (PMID 38587644, 2024). "We explored the correlation between FAP expression and clinical outcomes in simlukafusp alfa trials, spanning four tumor indications." (PMID 38558814, 2024). "This unique expression pattern positions FAP as a prospective biomarker for targeted tumor radiodiagnosis and therapy." (PMID 38543239, 2024). "Suppression of tumor growth was observed for the LL/2 stromal FAP+ cell depletion group (Ly5.1 → FAP-TK) and, to a lesser extent, for the hematopoietic FAP+ depletion group (FAP-TK → Ly5.1) compared with PBS injected controls." (PMID 38275890, 2024). "Upon entering the tumor stroma, these CAP-NPs were cleaved by FAP-a to efficiently release the encapsulated drug at the tumor site." (PMID 39092186, 2024). "It targets fibroblast-activation protein (FAP) on cancer-associated fibroblasts in tumor stroma and DR5 on tumor cells, again demonstrating the capacity of BATs to induce bystander cytotoxicity." (PMID 40061208, 2024). "We found that FAP was expressed highly across tumor tissue and rarely in normal colon or liver tissues, indicating it as a strong target candidate." (PMID 39335130, 2024). "This involves depleting or destroying all FAP-expressing cells, including stromal and cancer cells, which can indirectly inhibit tumor cell proliferation, increase collagen accumulation, decrease tumor vascular growth, and ultimately lead to rapid tumor death." (PMID 39758423, 2024). "The broad spectrum of FAP expressions in various malignancies has prompted numerous investigations on the pro- and anti-tumor impacts of FAP activities." (PMID 39766079, 2024). "FAP-IL-2v demonstrated improved tumor targeting compared to FAP-IL-2wt and showed antitumor efficacy in combination with anti-PD-L1 immune checkpoint blocker." (PMID 39204319, 2024). "Using this model, we have shown that FAP‐CAR‐T cells can significantly delay tumor growth and extend survival, despite antigen heterogeneity." (PMID 38975278, 2024). "Two of these populations, MYH11 + α-SMA+ CAFs in early stage tumors and FAP + α-SMA+ CAFs in advanced tumors, were associated with CD3+ and CD8+ T cell exclusion from the tumor nests." (PMID 39834587, 2024). "Reports of FAP’s ability to induce EMT solely through the modulation of transcriptional factors such as Slug and Snail also suggest the important role of FAP in tumor metastasis." (PMID 39579201, 2024). "Fibroblast activation protein (FAP) has become one of the most important molecular targets involved in the tumor microenvironment." (PMID 38334567, 2024). "FAP is considered a relatively clean target, as its expression is restricted to the tumor microenvironment and tumor draining lymph nodes, with little to no on-target-off-tumor toxicity expected as demonstrated in clinical trials with FAP-4-1BBL." (PMID 39444607, 2024).
tumor (continued). "The divalent one showed significantly higher FAP-specific tumor uptake than its monovalent counterpart." (PMID 39766079, 2024). "The relative contribution of these mechanisms to FAP-RLT efficacy remains unexplored, with responsiveness potentially varying based on factors such as the type of cells expressing FAP, tumor architecture, FAP-radioligand characteristics, and tumor biology." (PMID 38540204, 2024). "FAP has been reported to influence tumor growth via promoting tumor proliferation, invasion, angiogenesis, epithelial-to-mesenchymal transition, stem cell promotion, immunosuppression and drug resistance." (PMID 39086477, 2024). "At 1.5 h P.I., [99mTc]Tc-HYNIC-FAPI-04 uptake was clearly observed in FAP-positive U87MG tumor at 2.67 ± 0.35% ID/mL." (PMID 38695960, 2024). "The findings highlighted the sensitivity of 68Ga-FAPI-04-PET in monitoring tumor responses to the combined immunotherapy, potentially expanding the clinical role of FAP-targeted PET beyond tumor detection." (PMID 39283414, 2024). "While myCAFs express elevated alpha smooth muscle actin (αSMA) levels and are tumor restrictive, iCAFs have basal αSMA levels, express fibroblast activation protein (FAP), and secrete IL-6." (PMID 38891809, 2024). "Since the initial introduction of FAP-targeted compounds, the primary challenge in the successful implementation of radionuclide therapy has been the short tumor retention time of the molecules." (PMID 38540204, 2024). "FAPα is a marker of cancer associated fibroblasts (CAFs), which play an important role in the regulation of tumor microenvironment (TME) and in tumor evasion mechanisms." (PMID 39081320, 2024). "Our findings highlight a promising therapeutic approach for selectively and safely eliminating FAP+ cells within the tumor microenvironment." (PMID 38275890, 2024). "The potential to combine or label FAP-targeted bispecific antibodies is a promising avenue that introduces a fresh dimension to radiotherapy nuclide markers for FAP-targeted tumor therapy." (PMID 38543239, 2024). "This technique facilitates the evolution and optimization of FAP-targeting antibodies, culminating in the selection of antibodies exhibiting robust affinity, rapid internalization, and propensity for tumor accumulation." (PMID 38543239, 2024). "In that most of the tumor cells themselves rarely expressed FAP, hFAP overexpressed cell line FAP-HT1080 was established for the subsequent test." (PMID 39086477, 2024). "Fibroblast activation protein (FAP), a cell surface serine protease, plays roles in tumor invasion and immune regulation." (PMID 39055892, 2024). "[211At]FAPI1 administration selectively incorporates 211At into FAP expression sites, with the α rays not only directly exerting their anti-tumor effect but also being incorporated into the CAFs." (PMID 39519118, 2024). "Radiolabeled inhibitors targeting FAP administered to patients with HNCs have demonstrated localized uptake in tumor lesions, indicating activity above background levels." (PMID 39588373, 2024). "Despite the successes demonstrated in imaging studies, most of the currently available FAP-targeting radiotracers demonstrate a suboptimal tumor retention time in preclinical and clinical studies." (PMID 39073475, 2024). "​An example is the increased tumor uptake observed for 177Lu-labeled FAP-targeting homodimers ​120​." (PMID 39431018, 2024). "The extreme limiting dilution assay performed in vivo showed that FAP overexpression promoted liver tumor formation, with the tumor initiation frequency of these cells found to be much higher than that of the corresponding negative control cells." (PMID 38740736, 2024). "FAP-targeted radiotracers are extensively used for tumor imaging and FAP inhibitors such as LAF-237, PT-630 and talabostat are currently used." (PMID 39579201, 2024). "Using FAP as a target for anti-CAF therapy we have shown that depletion of FAP+ CAFs has potent direct anti-tumor activity." (PMID 38555315, 2024).
tumor (continued). "Key advantages inherent to FAP-2286 encompass elevated affinity for FAP binding, improved tumor accumulation, and prolonged tumor retention." (PMID 38543239, 2024). "FAP was expressed mainly on cancer-associated fibroblasts within the tumor stroma, whereas SSTR2 was expressed predominantly on tumor cells." (PMID 38176714, 2024). "mIF images visualized the spatial proximity of S100A6+ TGFBR1+ tumor cells and FAP+ CCN2+ fibroblasts." (PMID 39095854, 2024). "Depletion of the FAP-positive fibroblast population in transgenic mice led to cytokine-mediated hypoxic necrosis of both the tumor and the stroma." (PMID 39030445, 2024). "The enhanced imaging capability of 68Ga-NOTA-FAPI-RGD was attributed to its dual targeting of FAP and integrin αvβ3, making it more effective in detecting both tumor and stromal components." (PMID 39598465, 2024). "αSMA + FAP + mr-CAFs predominated in tumor tissue relative to adjacent normal tissue in patients with treatment-naïve ESCC." (PMID 39334513, 2024). "A recent study of NSCLC discovered multiple layers of FAP+ CAFs surrounding the tumor border, driving T-cell marginalization through the deposition and alignment of type XI and XII collagens." (PMID 39107856, 2024). "Moderate-strong FAP expression in the tumor stroma was present in 93.1% of CCA, 60.7% of extrahepatic metastatic HCC, 29.6% of primary HCC, 21.1% of FNH, and 11.6% of HCA." (PMID 39664608, 2024). "Fibroblast activation protein (FAP) is a key molecule in the field of oncology, with significant impacts on tumor diagnosis and treatment." (PMID 39758423, 2024). "L-amino-acid transporters (LAT-1) on glial cells form the basis of localisation of FET, whereas FAPI localizes to FAP which is present on tumor stroma especially in proximity to blood vessels." (PMID 39759219, 2024). "Although it has been confirmed that the fibroblast‐like transformation of tumor cells induced by TM can inhibit the malignant progression of tumors, the immunofluorescence (IF) experiments observed that FAP was activated after TM administration." (PMID 39206698, 2024). "The myofibroblast-like CAFs αSMA+ (myCAFs) were predominantly located proximal to the tumor, while the inflammatory CAFs FAP+ (iCAFs) were positioned distally from the tumor." (PMID 38606999, 2024). "Clinical use of [68Ga]Ga-FAPI-4 for tumor with FAP overexpression, has witnessed a tremendous growth, in last few years, in the staging of various types of cancers." (PMID 39050235, 2024). "Apart from that, the tumor weight was much higher in FAP-OE and IL-17-OE groups than the corresponding control groups." (PMID 38740736, 2024). "Fibroblast activating protein (FAP) is found on the surfaces of tumor stromal cells, macrophages, and tumor cells." (PMID 40337455, 2024). "The frequencies of tumor infiltrating CD45+CD3+ cells were increased from 0.38% ± 0.06% in Blank-T group to 1.55% ± 0.07% in FAP-CARTs group." (PMID 39086477, 2024). "Immunofluorescence staining of the excised tumor tissues post imaging validated the expression of FAP in the tumors." (PMID 39766079, 2024). "Compared to the collagen levels that increased significantly as tumor growth progressed, FAP levels remained unchanged during progression." (PMID 38891809, 2024). "These FAP-targeting probes allow better visualization of tumor boundaries, more accurate assessment of metastatic spread, and potential therapeutic response monitoring." (PMID 39770505, 2024). "Due to its high expression in the tumor stroma, numerous studies have used FAP as a marker of activated CAFs." (PMID 39030445, 2024). "Another strategy to improve tumor retention that is being explored, is the development of homodimers of FAP-targeting agents." (PMID 39073475, 2024). "We investigated the differential expression of FAP in various tumor types and its correlation with survival." (PMID 39055892, 2024).
tumor (continued). "In vitro studies using SCC15 cell lines corroborated FAP's involvement in cellular proliferation, apoptosis, and invasiveness, underscoring its influence on tumor aggressiveness." (PMID 38826849, 2024). "Remarkably, while the FAP in Panc-1-fl tumors was diffusely distributed in the tumor cells, these were more nuclear localized in the BxPC-3 models." (PMID 38891809, 2024). "FAP has also shown a tendency to further tumor infiltration through the brain ECM as well as secretion of pro-angiogenic factors and TGF-beta." (PMID 39759219, 2024). "The results showed very low tumor uptake in mice injected with [68Ga]Ga-AV02070, which indicates a very low FAP expression level in this tumor model." (PMID 38398552, 2024). "68Ga-FAP-2286 PET emerges as a pivotal tool for staging patients across cancer types characterized by robust tumor uptake, renal metabolism, and negligible renal accumulation." (PMID 38543239, 2024). "This made it difficult to distinguish between the murine FAP-expressing inflammatory cancer-associated fibroblasts (iCAFs) from the human FAP expressing tumor cells, owing to the known antibody cross-reactivity for human and mouse FAP." (PMID 38891809, 2024). "FAP-2286 has an advantage of accumulating in the FAP-positive tumor tissues for a relative long time." (PMID 38360704, 2024). "U-87 MG cells have low FAP expression in vitro, but in vivo these cells can recruit FAP-positive murine fibroblasts to the tumor site, mimicking the patient histopathology somewhat more closely." (PMID 39718718, 2024). "In hepatocellular carcinoma, FAP rises under tumor microenvironment hypoxia, aligning with adverse outcomes." (PMID 38558814, 2024). "[99mTc]Tc-FAPI-L3 was observed to accumulate in MDA-MB231 solid tumors (2.23% ID/g) and a co-injection of excess of FAPI was seen to block this tumor uptake (0.13 ± 0.06%ID/g), suggesting that tumor retention was FAP-mediated." (PMID 38695960, 2024). "Uptake of [68Ga]Ga-AV01088 to HEK293T:hFAP tumor is also FAP-mediated, as demonstrated by the significantly decreased tumor uptake obtained when co-injected with FAPI-04." (PMID 38398552, 2024). "Given the pressing need for novel therapeutic strategies in HNSCC and the intriguing roles of CAFs and FAP in tumor biology, this study aims to elucidate the functional implications of FAP within the context of HNSCC." (PMID 38826849, 2024). "It is known that FAP expression regulates tumor growth through a variety of mechanisms, including tumor cell proliferation, epithelial-to-mesenchymal transition, angiogenesis, drug resistance, and immunosuppression." (PMID 39766079, 2024). "Both [68Ga]Ga-AV01084 and [68Ga]Ga-AV01088 enabled the visualization of PSMA-expressing LNCaP tumor xenografts and FAP-expressing HEK293T:hFAP tumor xenografts in PET images acquired at 1 h post-injection." (PMID 38398552, 2024). "Tumor mesenchymal cells expressing FAP show enhanced adhesion and migration on substrates such as fibronectin or type I and type IV collagen." (PMID 39765634, 2024). "Targeting CAF markers such as FAP with chimeric CAR-T cells has shown promise in limiting tumor growth and enhancing host immunity, while presenting minimal side effects." (PMID 38693104, 2024). "The effect of FAP overexpression on alterations in substances and molecules in the tumor microenvironment needs to be further confirmed." (PMID 38740736, 2024). "Consistent with the cytotoxic potential of UniCAR T-cells obtained, the secretion of Interferon gamma (IFNγ), Interleukin 2 (IL-2) and Tumor Necrosis Factor alpha (TNFα) increase in a TM dose-dependent manner in both FAP+ tumor models and for all TMs." (PMID 39000348, 2024). "This is in line with a meta-analysis evaluating FAP expression in various tumors and showing significant correlation between high FAP expression and tumor progression." (PMID 37584717, 2024).